PDE6G (phosphodiesterase 6G)
Description:
Inhibitory gamma subunit of the rod-specific cGMP phosphodiesterase (PDE6) complex, which hydrolyzes 3',5'-cyclic GMP in the phototransduction cascade. The PDE6 holoenzyme consists of two catalytic subunits (PDE6A and PDE6B) and two inhibitory gamma subunits. Light-activated GNAT1 relieves gamma subunit-mediated inhibition, enabling the catalytic subunits to hydrolyze cGMP and thereby mediate visual signal transduction and amplification.
Synonyms: PDEG; RP57
Tractability: Small molecule: an approved drug acts on it; a structure with a bound ligand is known; a high-quality ligand is known; it belongs to a druggable protein family. Antibody: its Gene Ontology location is reachable by antibodies, with high confidence. PROTAC: ubiquitination databases record sites on it; a small molecule that binds it is known.
Gene: Protein-coding gene on chromosome 17 (81,650,459 to 81,663,112, reverse strand). Ensembl gene ENSG00000185527.
Subcellular location: Cell projection, cilium, photoreceptor outer segment
Subcellular location (Human Protein Atlas): Vesicles
Pathways (Reactome):
Sensory Perception: Activation of the phototransduction cascade; Inactivation, recovery and regulation of the phototransduction cascade
Signal Transduction: Ca2+ pathway
Gene Ontology:
Molecular function: protein binding; enzyme inhibitor activity; 3',5'-cyclic-nucleotide phosphodiesterase activity; cGMP binding; spectrin binding
Biological process: visual perception; positive regulation of epidermal growth factor receptor signaling pathway; positive regulation of G protein-coupled receptor signaling pathway
Cellular component: photoreceptor disc membrane; photoreceptor outer segment; photoreceptor outer segment membrane; plasma membrane; rod photoreceptor disc membrane
Genetic constraint (gnomAD): Loss-of-function variants: 10 observed, 11.69 expected, observed/expected ratio (o/e) 0.86, 90% interval 0.53 to 1.45. The upper end of that interval is the gene's LOEUF score, 1.45, which puts it in group 5 of 6, group 1 being the genes least tolerant of losing a copy. Missense variants: 102 observed, 115.51 expected, observed/expected ratio (o/e) 0.88, 90% interval 0.75 to 1.04. Synonymous variants: 41 observed, 45.47 expected, observed/expected ratio (o/e) 0.9, 90% interval 0.7 to 1.17.
Homologues: Orthologues: chimpanzee PDE6G (100% identical), macaque PDE6G (99% identical), pig PDE6G (98% identical), guinea pig PDE6G (97% identical), mouse Pde6g (97% identical), rat Pde6g (97% identical), zebrafish pde6gb (93% identical), tropical clawed frog PDE6G (78% identical), dog PDE6G (76% identical). Paralogues in human: PDE6H (78% identical).
Diseases named in the same sentence as PDE6G in open-access papers:
PDE6G is named in the same sentence as 23 diseases in open-access papers, as found by Europe PMC text mining. Sharing a sentence is not in itself a finding about the gene and the disease. The quoted sentences say what the papers report.
retinitis pigmentosa (9 papers, 2013 to 2024). Retinitis pigmentosa (RP) is an inherited retinal dystrophy leading to progressive loss of the photoreceptors and retinal pigment epithelium and resulting in blindness usually after several decades. "Other frequently observed genes are related to eye diseases (PDE6G has been linked to Retinitis Pigmentosa, and SIX6 to glaucoma, myopia, and retinal degeneration) or vascular processes (FLT1 linked to hypertension and heart disease)." (PMID 39505872, 2024). "PDE6G encodes the gamma subunit of cGMP-phosphodiesterase and is associated with diseases such as night blindness and retinitis pigmentosa." (PMID 38728357, 2024). "Analysis of variants in these individuals detected a homozygous novel c.69dupC, p.Arg24Glnfs*6 variant in PDE6G segregating with retinitis pigmentosa phenotype." (PMID 34662339, 2021). "We find that a retinitis-pigmentosa causing mutation in human PDE6G leads to the expression of a 3′UTR-encoded frameshift-isoform that is both destabilized and shows an inhibited ability to interact with its known binding partners PDE6A and PDE6B." (PMID 32727563, 2020). "Furthermore, as we demonstrate for a retinitis pigmentosa-causing mutation in the human phosphodiesterase PDE6G gene, misregulated translation into the 3′UTR is associated with the development of disease." (PMID 32727563, 2020). "Phosphodiesterase 6G (PDE6G) encodes the gamma subunit of cyclic GMP-phosphodiesterase and plays a role in the pathogenesis of retinitis pigmentosa." (PMID 36291758, 2022). "The last gene, rod phospodiesterase 6g (pde6g), functions in the regulation of cyclic GMP in rods following exposure to light, and mutations within this gene are associated with retinitis pigmentosa." (PMID 23437360, 2013). "PDE6G, the first of these genes, encodes one of the three subunits of Cyclic GMP-phosphodiesterase (PDE), and incorrect splicing of the gene is reported to lead to early-onset retinitis pigmentosa in a family-based mapping study." (PMID 26173456, 2015).
retinal degeneration (7 papers, 2018 to 2025). Degeneration of the retina. "Deletion of Pγr (encoded by the Pde6g gene) in mice leads to rapid retinal degeneration." (PMID 38110033, 2024). "The link between calcium influx and photoreceptor death in Pde6 mutants has been confirmed with genetic studies as Cngb1−/− knockout incorporated into Pde6g−/− and rd10 background delayed retinal degeneration in these mice." (PMID 40631959, 2025). "Similar to models of induced retinal degeneration, multiple transcripts involved in phototransduction (Pde6g, Cnga1-b1, Guca1a-1b) decreased after the onset of degeneration in rd10 rods." (PMID 35413909, 2022). "PRKG1 deficiency does not prevent retinal degeneration in Pde6g-/- mice but does so in Cngb1-/- mice, even though cell death in both cases is caused by cGMP elevation." (PMID 38350962, 2024). "Importantly, the PDE6AB catalytic dimer was reported to be present in a native-like conformation in the Pde6g KO retina prior to retinal degeneration, yet its cGMP hydrolytic activity was markedly impaired, suggesting that Pγr is necessary for expression of PDE6AB activity in vivo." (PMID 38110033, 2024). "Taking into account that deregulation calcium homeostasis plays a key role in retinal degeneration in rd10 mice, pathways involved the regulation, signaling, and/or exocytosis of this cation were also selected for validation, such as those related with Doc2b or Pde6g genes." (PMID 29847644, 2018). "The relative PDE6 protein levels were assessed by Western blotting and the rates of cGMP hydrolysis were measured in trypsin-treated retina lysates of Pde6g−/−, Pde6g−/−/Pde6ccpfl1, and C57BL/J mice (control) at P10 prior to retina degeneration." (PMID 38110033, 2024). "Finally, dual inhibition of CNG channel activity and PKG signaling may achieve the best effect, as the knockout of Prkg1 was found to slow retinal degeneration in Cngb1−/− but not in Pde6g−/− mouse models." (PMID 40631959, 2025).
autosomal recessive retinitis pigmentosa (3 papers, 2010 to 2021). Autosomal recessive retinitis pigmentosa (RP) is an autosomally recessive inherited retinal dystrophy leading to progressive loss of the photoreceptors and retinal pigment epithelium and resulting in blindness usually after several decades. "Mutations in PDE6G cause autosomal recessive retinitis pigmentosa, in which the dysfunction in retinal pigment epithelium is typical." (PMID 20463881, 2010). "Mutations in PDE6G are a rare cause of autosomal recessive retinitis pigmentosa." (PMID 31073882, 2019).
myopia (3 papers, 2019 to 2024). "Other suggestive signals were located near loci previously associated with retinal features, myopia, or abnormality of refraction, such as the TSPAN10/NPLOC4/PDE6G locus or the retinoid acid receptor beta RARB, associated with retinal vasculature in a previous GWAS." (PMID 38365752, 2024).
retinal dystrophies (2 papers, 2023 to 2026). "Integrated analysis of RNA-seq data from both Gm20541 and Msx2 mutant retinas indicated that ZNF124 is essential for maintaining normal retinal function by regulating Msx2 transcription, which in turn controls the expression of murine homologues of retinal dystrophy genes Rs1, Pde6g, and Pdc." (PMID 41708596, 2026). "This explains why pathogenic variants in PDE6A (OMIM #180071), PDE6B (OMIM #180072) and PDE6G (OMIM #180073) cause predominantly rod-involving retinal dystrophies, whereas pathogenic variants in PDE6C and PDE6H (OMIM #600827 and #601190) lead to retinal dystrophies which predominantly affect cones." (PMID 37433860, 2023).
Strabismus (2 papers, 2019 to 2020). A misalignment of the eyes so that the visual axes deviate from bifoveal fixation. "Thus, in summary, there was strong evidence that the causal variant underlying the association with strabismus acts as a cis-eQTL for TSPAN10 in neural tissue, and for PDE6G and ARL16 in certain other tissues." (PMID 31073882, 2019). "These variants were associated with reduced TSPAN10 gene expression in brain tissues, although such eQTL effects were also observed for the adjacent genes PDE6G and ARL16, suggesting that the risk of strabismus could be mediated through any one or more of these genes." (PMID 31073882, 2019).
cone-rod dystrophy (1 paper, 2018). Inherited retinal dystrophies that belong to the group of pigmentary retinopathies. "Here, we present the initial results of a pilot study targeting zebrafish orthologs of five human genes linked to RP: PDE6A, PDE6B, PDE6G, ABCA4, and RHO (note, ABCA4 is also linked to cone-rod dystrophy)." (PMID 30186835, 2018).
retinoblastoma (1 paper, 2025). A malignant tumor that originates in the nuclear layer of the retina. "Among the most upregulated genes were KRT5, KRT19, LCN2, SLP1 and S100A9, while GNAT1, PDE6G, WIF1, FRZB, and RHO were among the top downregulated genes in retinoblastoma." (PMID 40395327, 2025).
Usher syndrome (1 paper, 2018). A syndromic diseae characterized by the association of sensorineural deafness (usually congenital) with retinitis pigmentosa and progressive vision loss. "While Usher syndrome etiology is classically regarded as stemming from genes that do not contain PDE6A, PDE6B, or PDE6G, researchers have yet to identify whether the mechanisms that underlie vision loss in Usher syndrome are identical to those present in non-syndromic RP." (PMID 29472945, 2018).
visual disorders (1 paper, 2024). "Overall, a better understanding of the mechanism of PDE6 maturation and the roles of AIPL1 and Pγ will help to design therapeutic strategies to treat visual disorders linked to mutations in the AIPL1, PDE6G, and PDE6H genes." (PMID 38110033, 2024).
tumor (2 papers, 2018 to 2024). "In addition, the expression levels of rod-enriched genes, including NRL, NR2E3, CNGA1, and PDE6G, were depleted in organoids, consistent with tumor, but high in normal retina, where rods outnumber cones." (PMID 30353124, 2018). "The comparisons between tumor tissue and normal tissue showed that PDE6G and CYP3A4 expression, but not CEL expression, in PCa tissue was considerably higher than that in normal prostate tissue." (PMID 38297388, 2024).
cancer (1 paper, 2022). A tumor composed of atypical neoplastic, often pleomorphic cells that invade other tissues. "However, no clear association of PDE6G with cancer has emerged." (PMID 36291758, 2022).
PDE6G also shares sentences with these, for which no sentence is quoted: breast carcinoma (3 papers); benign prostatic hyperplasia (1); breast tumor (1); congenital stationary night blindness (1); glaucoma (1); heart disease (1); Hypertension (1); Macular dystrophy (1); night blindness (1); prostate carcinoma (1); retinal diseases (1).